DKK1 (dickkopf Wnt signaling pathway inhibitor 1)
Diseases named in the same sentence as DKK1 in open-access papers (continued):
Sharing a sentence is not in itself a finding about the gene and the disease.
lung carcinoma (continued). "Subsequently, the declines of Dkk-1 in metastatic lung cancer cells removed the suppression on microglia and enhanced microglial activation in metastatic niche." (PMID 33384994, 2020). "The analyses of ELISA further confirmed an increment of extracellular levels of Dkk-1 in BMECs after treatment with lung cancer cells-derived exosomes." (PMID 33384994, 2020). "Collectively, our results suggested that a reduction of endogenous Dkk-1 in lung cancer cells after colonization into brain would control microglia to acquire a pro-tumorigenic phenotype." (PMID 33384994, 2020). "The levels of Dkk-1 mRNA were significantly increased in HBMECs in the presence of the indicated lung cancer cell-derived exosomes (p = 0.008)." (PMID 33384994, 2020). "Because the arrival of lung cancer exosomes was prior to lung cancer cells colonization into brain, the release of Dkk-1 from brain endothelium after uptake of exosomes seemed to be an early event." (PMID 33384994, 2020). "Subsequently, the decline of Dkk-1 in the metastatic lung cancer cells would strengthen the extent of microglia activation and infiltration into in tumor mass." (PMID 33384994, 2020). "To examine the reliability of our axial lsFCS-based analysis for the determination of KD values of ligand-receptor interactions, we studied DKK1-eGFP binding to NCI-H1703 lung cancer cells expressing LRP6-mCherry in widely differing amounts." (PMID 32441251, 2020). "Further in vitro experiments demonstrated that brain metastatic lung cancer cells with low Dkk-1 induced microglia to obtain an anti-inflammatory property, known as a feature of brain micro-metastases." (PMID 33384994, 2020). "Taken together, these results implied a possibility that the levels of Dkk-1 in lung cancer cells became descend after colonization into brain." (PMID 33384994, 2020). "To further demonstrate that Dkk-1 secreted by BMECs contributed to the suppressive effect of lung cancer cells-derived exosomes on microglia, we used RNAi to knock down the levels of Dkk-1 in MBMECs (bEnd.3 cells)." (PMID 33384994, 2020). "Further results indicated that lung cancer cells-derived exosomes induced a release of endogenous Dkk-1 from brain endothelium, which rendered microglia to acquire a pro-tumorigenic feature in pre-metastatic niche." (PMID 33384994, 2020). "To further confirm the reduction of Dkk-1 in lung cancer cells after colonization into brain, we performed the in vivo selection of highly metastatic lung cancer cells as described in other study." (PMID 33384994, 2020). "Nos2 is known to promote drug resistance in lung cancer by activation of the canonical Wnt pathway through inhibition of DKK1 and to promote the growth of CSCs in glioma via the Notch pathway." (PMID 31796785, 2019). "EZH2 suppresses Dkk1 transcription via trimethylation of H3K27me3, which has been detected in lung cancer." (PMID 28332284, 2017). "Our in vivo studies also showed that DKK1‐overexpression in lung cancer cells exhibited CSC phenotype and were more aggressive." (PMID 27240974, 2016). "Similar to VM, DKK1 was frequently expressed in large cell lung cancer (41/51, 80.39%) and poorly differentiated lung cancer (64/83, 77.11%)." (PMID 27240974, 2016). "The expression of DKK1 was detected among three lung cancer lines representing distinct histological entities, namely, H460 (large cell lung cancer), H1299 (lung adenocarcinoma) and A549 (lung adenocarcinoma)." (PMID 27240974, 2016). "Non‐small cell lung cancer cell lines with overexpressed or silenced DKK1 highlighted its role in the restoration of mesenchymal phenotypes and development of CSC characteristics." (PMID 27240974, 2016). "The DKK-1 concentration was significantly higher in the serum of lung cancer patients than in that of other malignant tumor patients or healthy people." (PMID 20920327, 2010).
lung carcinoma (continued). "Our previous studies have demonstrated that CSC induces polycomb-mediated repression of Dkk-1 in lung cancer cells and cultured normal respiratory epithelia." (PMID 21048943, 2010). "CSC-exposure as well as Dkk-1 knock-down enhances Wnt-5a expression, and significantly increases proliferation and tumorigenicity of lung cancer cells." (PMID 21048943, 2010). "Gene expression profile analysis of lung and esophageal carcinomas revealed that DKK-1 was highly transactivated in the great majority of lung cancers and esophageal squamous cell carcinomas." (PMID 21029453, 2010). "In lung cancer cells ASCL1 negatively regulates the expression of Dickkopf homologue 1 (DKK1), an antagonist of the Wnt/β-catenin signalling pathway which is involved in the development of the exocrine pancreas and in pancreatic beta cell proliferation." (PMID 19744316, 2009). "ASCL1 has been found to repress DKK1 transcription, a negative regulator of the Wnt signalling pathway in lung cancer cells, and is also the first transcriptional repressor identified for DKK1." (PMID 19744316, 2009). "In addition, analysis of public data (GSE121634) demonstrated increased DKK1 expression in lung cancer cells resistant to another EGFR-TKI, erlotinib, in HCC827 and HCC4006 cells." (PMID 40025612, 2025). "Moreover, DKK1 was identified as a potential anticancer target across various cancer types beyond gefitinib-resistant lung cancer." (PMID 40025612, 2025). "Interestingly, the serum DKK1 level in the drug-resistant group was higher than that in the sensitive group, suggesting that DKK1 can be used as a marker for lung cancer screening, diagnosis, and chemotherapy efficacy evaluation." (PMID 37835450, 2023). "DKK1 is found to be substantially more expressed in lung cancer tissues than normal controls." (PMID 36506325, 2022). "Animal models of brain metastases showed that upon exosome internalisation of lung cancer cell-derived exosomes, endothelial cells send suppressive signals toward microglia, via the release of endogenous Dkk-1, contributing to the creation of an immunosuppressive environment." (PMID 35327593, 2022). "However, it has also been reported that a decrease in DKK-1 in metastatic lung cancer cells eliminates microglial inhibition and increases the risk of metastasis." (PMID 35907982, 2022). "Previous study has demonstrated that miR-203 could bind to the 3′UTR of DKK1 and then regulate the characteristics of lung cancer cells." (PMID 35410350, 2022). "In nonsmall cell lung cancer, RYR2 mutation may prolong survival via downregulation of DKK1 and upregulation." (PMID 35975176, 2022). "In in vitro experiments, up-regulation of DKK1 expression in the SBC-3 lung cancer cell line enhanced the proliferation, migration, and invasion of cells, and colony formation; in in vivo experiments, up-regulation of DKK1 expression promoted the metastasis of lung cancer cells to bone." (PMID 33988228, 2021). "Furthermore, the authors were able to demonstrate a significant unfavorable impact on overall survival of high DKK1 expression in surgically treated lung cancer and EC samples." (PMID 34638464, 2021). "Therefore, it was a possibility that the decline of Dkk-1 in lung cancer cells was a result of lung cancer cells survival in the brain." (PMID 33384994, 2020). "Downregulation of CKAP4 or DKK1 in A549 lung cancer cells suppressed AKT activity through PI3K." (PMID 33614703, 2020). "The lung cancer-derived exosomes induced brain endothelial cells to secrete Dkk-1." (PMID 33384994, 2020). "Collectively, our results supported the hypothesis that BMECs might release endogenous Dkk-1 after internalization of lung cancer-derived exosomes from the peripheral vascular system and Dkk-1 might suppress the activation of microglia." (PMID 33384994, 2020). "Despite these studies, the involvement of DKK1 in lung cancer bone metastases was still unclear." (PMID 29108326, 2017).
lung carcinoma (continued). "Our results suggested that DKK1 plays an important role in lung cancer bone metastasis, and serum DKK1 may be a potential tumor biomarker of clinical prognostic value." (PMID 29108326, 2017). "A recent study reported that DKK1 can suppress the progression of colon cancer but elevates the invasion capacity of esophageal carcinoma cell line EC-9706 and diminishes the survival of lung cancer patients." (PMID 26967563, 2016). "A previous report has shown that DKK1 is also highly expressed in NSCLC, and may be useful as a novel diagnostic and prognostic marker for lung cancer." (PMID 27240974, 2016). "To characterize the contributions of Dickkopf‐1 (DKK1) towards the induction of vasculogenic mimicry (VM) in non‐small cell lung cancer (NSCLC), we evaluated cohorts of primary tumours, performed in vitro functional studies and generated xenograft mouse models." (PMID 27240974, 2016). "The expression and roles of DKK-1 are different in various cancers, current studies have reported that overexpression of DKK-1 is found in many malignant tumors, including lung cancer, esophageal carcinomas, cervical cancer, and HCC, indicating a potential oncogenic function of DKK-1." (PMID 25116444, 2014). "DKK-1, however, is also reported to be overexpressed in tissues and serum of lung cancers and esophageal squamous cell carcinoma, suggesting that DKK-1 may act as pro-oncogene." (PMID 20920327, 2010). "Thus, ASCL1 is likely to negatively regulate DKK1 transcription in these tumours, as has been shown to occur in A549 lung cancer cells." (PMID 19744316, 2009). "In addition, a number of recent studies have shown that DKK1 is positively correlated with lung cancer stage and tumor metastasis, and that it may promote lung cancer invasion and proliferation." (PMID 36506325, 2022). "The function of DKK1 expression in lung cancer progression and prognosis remains unclear." (PMID 35907982, 2022). "Having demonstrated that brain endothelium-derived Dkk-1 directly triggered microglia to promote the formation of pre-metastatic niche, we next sought to evaluate whether Dkk-1 was also involved in the progression of lung cancer metastasis to brain." (PMID 33384994, 2020). "As our previous studies described, we have found that lung tumor cell derived DKK1 increases the level of β-catenin and negatively regulates osteoblast differentiation, indicating that lung cancer produced DKK1 may be an important mechanistic link between NSCLC and bone metastases." (PMID 29108326, 2017). "In addition, DKK1 was found in 11 out of 23 lung cancer specimens." (PMID 17245340, 2007). "Recent studies have demonstrated a novel pathway where DKK1 binds to its novel receptor CKAP4 and activates the Akt-signaling pathway for cancer progression in lung cancer, pancreatic cancer, and esophageal cancer." (PMID 39858622, 2025). "In a study on lung and pancreatic cancer, co-expression of DKK1 and CKAP4 was found to be negatively correlated with the prognosis and recurrence-free survival of pancreatic and lung cancer." (PMID 39107271, 2024). "MiR-31 directly inhibits the expression of Dkk-1 and DACT3 in lung cancer cells as well as normal respiratory epithelium." (PMID 38309281, 2023). "In lung carcinoma, G9A participates in the activation of WNT signaling by suppressing relating inhibitors like APC2, DKK1, and WIFI, which ultimately promotes cell proliferation." (PMID 37739945, 2023). "So far, the serum tumor markers used in early lung cancer diagnosis and recurrence monitoring include CEA, secreted protein Dickopf-1 (DKK1), etc." (PMID 35712471, 2022). "In lung cancer, EZH2 was upregulated and increased H3K27me3 to repress Dickkopf‐1 (Dkk‐1) expression." (PMID 31855281, 2020). "DKK1/DKK3-CKAP4 signaling axis was shown to promote progression of ESCC, lung cancer, and pancreatic cancer through PI3K and AKT pathway." (PMID 33614703, 2020).
lung carcinoma (continued). "To further elucidate the effect of Dkk-1 on microglia activity, we firstly performed the inhibition experiment in co-cultured system using GW4869, which inhibited the secretion of lung cancer cell derived-exosomes." (PMID 33384994, 2020). "MSC conditioned medium favored lung cancer cell proliferation and lung cancer cells stimulated the expression of IL-6, IGF-1, VEGF and DKK1 on MSCs." (PMID 26582222, 2015). "Herein, we report that CSC induces expression of miR-31 targeting several Wnt signaling antagonists including Dickkhopf-1 (Dkk-1) and DACT3 in normal human respiratory epithelia as well as lung cancer cells." (PMID 21048943, 2010). "Over-expression of miR-31 markedly diminished Dkk-1 and DACT3 expression levels in normal respiratory epithelia and lung cancer cells." (PMID 21048943, 2010). "Collectively, these experiments strongly suggested that miR-31 modulates Dkk-1 and DACT3 via post-transcriptional and translational-inhibitory mechanisms in cultured normal respiratory epithelia and lung cancer cells." (PMID 21048943, 2010). "In addition, the activation of the P13K/AKT pathway by the binding of DKK-1 to the novel CKAP4 receptor resulted in increased proliferation of normal canine kidney epithelial cells and human pancreatic and lung cancer cells." (PMID 38067123, 2023). "DKK1 has been reported as a tumor suppressor in colon cancer (CC) or as an oncogene abnormally expressed in tumor cells or overexpressed in many cell lines and HCC, lung cancer, BC, cervical cancers, and glioma." (PMID 37834160, 2023). "We have evaluated the method by measuring the binding of the Wnt signaling inhibitors human Dickkopf1 (DKK1) and Dickkopf2 (DKK2) to the Wnt co-receptor lipoprotein-receptor related protein 6 (LRP6) in human lung cancer (NCI-H1703) and human embryonic kidney (HEK293T) cells." (PMID 32441251, 2020). "Fox example, Dickkopf-related protein 1 (DKK1), induced by SOX2, positively regulates myeloid-derived suppressor cells in the tumor microenvironment and provides metastatic latency and immune evasion in lung cancer by protecting cells from NK cells." (PMID 31080551, 2019). "Recently, latent competent human breast and lung carcinoma cells have been proposed to express stem‐cell‐like SOX transcription factors, which–through the expression of WNT inhibitor DKK1 (dickkopf WNT signaling pathway inhibitor 1)–self‐impose a slow proliferating state." (PMID 28017284, 2017). "However, the expression level of DKK-1 in primary lung cancer and its relationship with clinicopathological factors has not been examined, therefore, and the biological roles of DKK-1 in lung cancer cells are still unclear." (PMID 24612589, 2014). "To exclude whether tumor-derived exosomes carried Dkk-1 and transferred to brain endothelial cells, we examined the levels of Dkk-1 in the different lung cancer cells-derived exosomes and found that there was no Dkk-1 detected in lung cancer cells-derived exosomes." (PMID 33384994, 2020). "Clinically, patients with lung cancer receiving anti-PD-1 exhibited increased magnetic resonance imaging contrast enhancement in the brain, suggestive of BBB perturbations, and increasing plasma DKK1 levels correlated with higher BrM incidence in nonresponders." (PMID 41525686, 2026).
colon carcinoma (59 papers, 2007 to 2026). "Silencing of DKK-1 in colon cancer has been associated with microsatellite instability; its expression is regulated by both promoter methylation as well as histone tail modifications." (PMID 25322458, 2014). "As most colon tumors have mutations that render a constitutively active Wnt/β-catenin pathway, the importance of DKK-1 induction for Wnt/β-catenin antagonism by 1,25(OH)2D3 is unclear." (PMID 24202444, 2013). "Several studies have reported the association of DKK1 with colon cancer." (PMID 38334454, 2024). "Indeed, DKK1 nuclear staining was observed in colon cancer cells and associated with increased expression of genes involved in cellular detoxification and survival." (PMID 27367730, 2016). "Consequently, the reduction and loss of DKK1 expression as a tumor-suppressive activity have been reported in human cancers such as malignant melanoma and colon cancer." (PMID 25144498, 2014). "Indeed, up-regulation of DKK1 causes a decrease in colon cancer cell proliferation, clonogenicity, migration, and invasiveness." (PMID 24325363, 2013). "This study aimed to test the hypothesis that the enhanced gene expression of the WNT signaling pathway antagonist, DKK1 by genistein treatment is associated with epigenetic modifications of the gene in colon cancer cells." (PMID 22815877, 2012). "Additionally, serum DKK1 levels could serve as a biomarker to identify both cancer and adenoma, offering diagnostic possibilities for early‐stage colon tumors." (PMID 38334454, 2024). "In conclusion, this study demonstrates that genistein inhibits colon cancer cell proliferation and induces G2 phase arrest through upregulation of the Wnt pathway antagonist DKK1." (PMID 40969596, 2025). "In the present study, DKK1 suppressed the proliferative potential of colon cancer cell lines, which was restored by silencing of DKK1." (PMID 38334454, 2024). "Next, we examined the functional effects of DKK1 on colorectal tumors using the human colon cancer cell line HCT116." (PMID 38334454, 2024). "Previously, we have shown that methylation of the WNT target genes APCDD1, AXIN2 and DKK1 predicts poor prognosis in stage II colon cancer patients." (PMID 34068407, 2021). "A translational clinical study was conducted, investigating the effect of pre-operative decitabine on the methylation and expression of WNT target genes APCDD1, AXIN2 and DKK1 and global methylation in colon cancer patients." (PMID 34068407, 2021). "GSTO1 knock-down by the inhibitor C1-27 in colon cancer cell line HCT116 resulted in down-regulation of Dickkopf-related protein 1 (DKK1), thombospondin 1 (THBSS1) and CAV-1." (PMID 31889941, 2019). "A downregulation of DKK1 has been observed in melanoma and colon cancer where it functioned as a tumor suppressor gene." (PMID 31285694, 2019). "Another study in the same context revealed that DKK1 expression is decreased in human colon tumors, indicating that this molecule acts as a tumor suppressor by inhibiting the expression of target genes of the beta-catenin-TCF pair." (PMID 31568519, 2019). "DKK-1 expression has been found to be down-regulated in human colon cancer, contributing to activation of the Wnt/β-catenin pathway." (PMID 28455497, 2017). "This inhibitory role of DKK-1 in Wnt/β-catenin signaling is supported by the downregulation of DKK-1 in human colon cancers and the correlation between high DKK-1 expression and favorable responses to chemotherapy in brain tumors." (PMID 28938611, 2017). "These include intestinal and colon cancers where DKK1 transcriptional silencing is the result of promoter hypermethylation." (PMID 27367730, 2016). "Studies using xenograft models of colon cancer showed opposite results, where reduced tumour growth was observed with overexpression of DKK1." (PMID 27367730, 2016). "It has also been proposed that DKK1 silencing in colon cancer suggests a tumour suppressor role for DKK1 and thus the need for its repression to allow tumour growth." (PMID 27367730, 2016).